TF (transferrin)
Diseases named in the same sentence as TF in open-access papers (continued):
Sharing a sentence is not in itself a finding about the gene and the disease.
sickle cell anaemia (7 papers, 2013 to 2024). "It is tempting to postulate that both transferrin and ferritin could be a link between the inflammatory process underlying sickle cell disease and serum PON-1 activities." (PMID 31366068, 2019). "Serum ferritin was assayed and transferrin saturation derived in 97 steady state sickle cell anaemia children." (PMID 34795732, 2021). "Serum ferritin level was greater than 300 mg/ml in 14 (14.4%) subjects and transferrin saturation >45% in six (6.2%) subjects with sickle cell anaemia." (PMID 34795732, 2021). "Both transferrin and ferritin were the main predictors of arylesterase and paraoxonase activities in the patients with sickle cell disease." (PMID 31366068, 2019). "The transferrin saturation model was a more successful method to identify IDA among children with sickle cell anaemia but there is a need for a collaborative study to draw conclusions from a larger pool of patients." (PMID 24363884, 2013). "Moreover, in this study, sickle cell disease patients with PON-1 RR polymorphism had a lower serum ferritin and iron concentration and transferrin saturation when compared with those with QQ or QR polymorphisms." (PMID 31366068, 2019). "Here, the increased levels of transferrin and ferritin were the main predictors of arylesterase and paraoxonase activities in the patients with sickle cell disease, both being responsible for approximately 25% of the arylesterase activity and 31% of the paraoxonase activity." (PMID 31366068, 2019). "The study revealed the need for periodic determination of iron over load in children with sickle cell anaemia in steady state that are not chronically transfused using either serum ferritin or transferrin saturation assay." (PMID 34795732, 2021). "A recent study on erythrocyte PMVs and other circulating PMV subtypes in sickle cell disease found that they did not detect Tissue Factor+ (TF+) PMVs, monocyte (CD14+) PMVs (MPMVs) or endothelial cell (CD 144+, CD146+, CD62E+) PMVs (EPMVs) in their samples." (PMID 26259622, 2015). "Contrastingly, another group did not just detect TF+ PMVs, EPMVs and MPMVs, but concluded that the observed increase gave weight to the hypothesis that sickle cell disease is an inflammatory state with endothelial cell and monocyte activation along with abnormal vessel wall activity." (PMID 26259622, 2015).
triple-negative breast carcinoma (7 papers, 2020 to 2023). An invasive breast carcinoma which is negative for expression of estrogen receptor (ER), progesterone receptor (PR), and human epidermal growth factor receptor 2 (HER2). "Our previous work also reported TF expression associated to vimentin expression in Triple Negative Breast Carcinoma (TNBC) but also in CTCs isolated from metastatic breast cancer patients." (PMID 35805061, 2022). "A similar approach was described in a study reporting the combination of anti-TF CAR-NK cell therapy with chimeric antibody-like homodimer immunoconjugates that also target TF, called ICON and L-ICON, in triple-negative breast cancer." (PMID 35242135, 2022).
tuberculosis (7 papers, 2012 to 2022). A chronic, recurrent infection caused by the bacterium Mycobacterium tuberculosis. "However, a retrospective analysis from an HIV-infected human cohort from Gambia revealed a significantly greater risk of developing tuberculosis in patients having lower serum transferrin, iron, and hemoglobin, and higher levels of ferritin and hepcidin." (PMID 31108902, 2019). "Changes in TF expression have been reported in many inflammatory thrombotic conditions, as well as in infections such as tuberculosis." (PMID 35100311, 2022). "However, further studies are needed in future to demonstrate the relevance of TF expression in tuberculosis disease pathology employing appropriate animal models." (PMID 23029190, 2012). "In addition, transferrin-conjugated QDs may constitute an effective drug delivery system for tuberculosis therapy." (PMID 27113139, 2016).
ulcerative colitis (7 papers, 2017 to 2025). An inflammatory bowel disease involving the mucosal surface of the large intestine and rectum. "Decreased intestinal transferrin is found in germ-free mice and human patients with ulcerative colitis, which are characterized by impaired intestinal immunotolerance." (PMID 38274126, 2024). "•PON-1, GPx, CAT, albumin, transferrin, and R–SH indicate ulcerative colitis flares." (PMID 39368456, 2024). "Our study shows higher levels of SE, CRP, Ag PLT ASPI, Ag PLT TRAP, Ag PLT ADP, Le, PLT, FCP, TNF-α, and IL-6 in patients with ulcerative colitis, when compared to the healthy controls, as well as lower levels of vitamins B12, B6, serum Fe, and transferrin saturation." (PMID 36984554, 2023).
Arthritis (6 papers, 2015 to 2025). Inflammation of a joint. "In vivo, a gradual increase in TF mRNA expression over 7 days has been demonstrated in mice with antigen-induced arthritis and increased TF activities along with increased fibrinogen concentrations have been found in inflamed synovial fluid from human arthritis." (PMID 26116380, 2015).
bacteremia (6 papers, 2020 to 2025). "We further examined the major plasma iron parameters (iron, ferritin, and transferrin) in patients with bacteremia." (PMID 40607920, 2025). "In serum, the transferrin-bound Fe3+ fraction will be the predominate ionic form for the survival of SEn during the transient bacteremia phase." (PMID 35308377, 2022). "By contrast, inactivation of acinetobactin biosynthesis alone impairs growth on human serum, transferrin, and lactoferrin, and severely attenuates survival of A. baumannii in a murine bacteremia model." (PMID 33075115, 2020). "We found that ferritin level showed a significant correlation with hepcidin concentrations in all patients with bacteremia, whereas circulating iron level and transferrin level did not." (PMID 40607920, 2025). "Our results agreed with a recent study published by Sheldon and Skaar where they demonstrated that the deletion of gene basG impairs growth on human serum, transferrin or lactoferrin as sole iron sources, and severely attenuates survival of A. baumannii ATCC 17978 in a murine bacteremia model." (PMID 34675911, 2021).
beta thalassemia (6 papers, 2003 to 2025). Beta-thalassemia (BT) is characterized by deficiency (Beta+) or absence (Beta0) of synthesis of the beta globin chains of hemoglobin (Hb). "Beta-thalassemia patients with HFEgene mutations; analysis of serumferritin and transferrin saturation." (PMID 41281279, 2025). "A comprehensive review of articles published from 2010 to 2024 in the PubMed database wasconducted using the keywords »In patients with Transferrin, Serum Ferritin« and »Beta-Thalassemias«." (PMID 41281279, 2025). "The model was also applied to predict the outcome of a proposed treatment of beta-thalassemia with transferrin injections, and the difference between intravenous and intragastric iron supplementation." (PMID 30608934, 2019). "By modulating the degree of change in kInBM (rate constant for transfer of iron from transferrin to bone marrow) the model could simulate thalassemia intermedia and thalassemia major." (PMID 30608934, 2019). "Transferrin (TRF) has been shown to reverse iron accumulation in experimental models, but its role in transfusion-dependent beta-thalassemia (TDT) patients remains unclear." (PMID 41281279, 2025). "Transferrin saturation shows a negative correlation with BMD in patients with transfusion-dependent beta-thalassemia." (PMID 36568116, 2022).
celiac disease (6 papers, 2014 to 2024). An autoimmune genetic disorder with an unknown pattern of inheritance that primarily affects the digestive tract. "However, other evidence suggests that even with a gluten-free diet, patients with celiac disease can present lower anthropometric values, in addition to nutritional deficiencies, such as lower levels of B6 and B12 vitamins, folic acid, iron, and transferrin." (PMID 31583132, 2019).
iron overload diseases (6 papers, 2013 to 2025). "Accordingly, increased ferritin levels were previously observed in iron overload diseases, where the storage proteins, including both ferritin and transferrin, are abundant/saturated and serve as a diagnostic sign." (PMID 38078368, 2024). "On the other hand a patient with decreased plasma transferrin can suffer from iron overload diseases and protein malnutrition." (PMID 23978045, 2013).
kidney damage (6 papers, 2020 to 2025). "The reduction in serum transferrin suggests a decreased capacity for iron transportation due to kidney damage." (PMID 40277801, 2025). "Among these, NAG, NGAL, albumin, and transferrin showed the greatest significance, suggesting that these biomarkers are more sensitive for diagnosing kidney damage due to tobacco use." (PMID 35887529, 2022). "In this context, albuminuria could identify patients with subclinical kidney damage (glomerular or tubular), while transferrin and GM2AP, biomarkers of tubular damage, would only identify this type of damage." (PMID 34768464, 2021).
metabolic disorders (6 papers, 2015 to 2025). "Addressing the potential role of the newly identified TF variants represents a crucial step towards understanding the regulatory mechanisms underlying physiological states as well as human diseases, especially cancer and metabolic disorders." (PMID 25590302, 2015). "Lastly, it is not clear what effect the found transferrin mutation might have concerning psychiatric symptoms and what other findings could have been made concerning metabolic diseases." (PMID 40301838, 2025). "In the nutrition indices of burn patients, both transferrin and albumin are acute phase proteins synthesized in the liver, and the metabolism of proteins can be sensitively reflected in patients without metabolic disorders." (PMID 27375697, 2016). "Overall, the OD values in our ELISA test of AO, TF, and C5 were significantly higher in cattle resistant to bTB than in those with bTB (≥1.4x, ≥1.7x, ≥1.7x, respectively), regardless they were suffering or not from other unrelated infectious or metabolic diseases (p < 0.001)." (PMID 34869715, 2021).
osteoporosis (6 papers, 2019 to 2025). A condition of reduced bone mass, with decreased cortical thickness and a decrease in the number and size of the trabeculae of cancellous bone (but normal chemical composition), resulting in increased fracture incidence. "Evaluation revealed hypogonadotropic hypogonadism, elevated serum ferritin (>2000 ng/mL), transferrin saturation of 93.8%, and osteoporosis (lumbar spine T-score −3.3; femoral neck −3.7)." (PMID 40979821, 2025). "Cochran’s Q-test indicated heterogeneity between TSAT and AS, as well as transferrin and osteoporosis, transferrin and RA, transferrin and AS." (PMID 39345879, 2024).
restless leg syndrome (6 papers, 2017 to 2025). "Studies have also correlated ferritin/transferrin disruption with NPS, like night agitation and restless leg syndrome." (PMID 38877658, 2024).
sleep disorder (6 papers, 2017 to 2025). A change from the patient's baseline sleeping pattern, in the hours slept and/or an alteration/dysfunction in the stages of sleep. "Additionally, the sleep disorder group showed significantly lower levels of body mass index, peripheral albumin, prealbumin, hemoglobin, and transferrin than the normal sleep group (all P < 0.001)." (PMID 41584611, 2025). "Endorsing simple routine blood tests, including inflammatory markers such as C-reactive protein, ferritin, transferrin, and vitamin D levels, may favorably complement caregiver observations and ambulatory sleep recordings, leading to a sleep disorder diagnosis and consequent therapy." (PMID 36226108, 2022).
small cell lung carcinoma (6 papers, 1991 to 2024). Small cell lung cancer (SCLC) is a highly aggressive malignant neoplasm, accounting for 10-15% of lung cancer cases, characterized byrapid growth, and early metastasis. "Tf synthesis in small cell lung cancer cells also acts as an autocrine regulator of cellular proliferation, allowing these cells to continue proliferating under transferrin-free conditions." (PMID 18509548, 2008). "A longitudinal study of iron status markers (haemoglobin (Hb), serum (S-) iron, S-transferrin, transferrin saturation, S-ferritin) was performed in 31 chemotherapy treated patients with small cell lung cancer." (PMID 1657106, 1991). "Interestingly, TF expression in small-cell lung cancer tissue was lower than that in normal lung tissue." (PMID 28055955, 2017).
Splenomegaly (6 papers, 2013 to 2025). Abnormal increased size of the spleen. "Taken together, rubiadin significantly alleviated the splenomegaly, and reduced the serum iron and transferrin saturation caused by iron overload." (PMID 39941155, 2025). "The presence of splenomegaly and a positive history for thrombotic complications were associated with elevated concentrations of RMPs, PMPs, EMPs and TF+MPs (p < 0.05 for all) in the MPN group." (PMID 34357048, 2021). "Rubiadin significantly reversed splenomegaly and abnormal elevation of serum iron, TIBC, and TF% caused by high-iron feed." (PMID 39941155, 2025). "Based on the IVM model splenomegaly (P < 0.05), wasting (P < 0.05), sex (P < 0.05), transferrin (P < 0.01) and ferritin (P < 0.001) concentrations, were significantly associated with haemoglobin concentration in children with falciparum infection." (PMID 23497273, 2013). "Additionally, we found that rubiadin significantly decreased the serum iron (SI), transferrin saturation (TF%) levels and duodenal iron content and relieved splenomegaly and increased the hepatic hepcidin in high-iron-fed mice." (PMID 39941155, 2025).
acute coronary syndrome (5 papers, 2014 to 2022). Signs and symptoms related to acute ischemia of the myocardium secondary to coronary artery disease. "The association between TF+ MMVs and oxLDL-C has previously been demonstrated in acute coronary syndrome." (PMID 26925191, 2016). "The procoagulant effect of PCSK9 may also play a pathogenetic role within the inflamed microenvironment of a disrupted atherosclerotic plaque by stimulating TF expression in resident macrophages favoring the formation of the occluding thrombus during acute coronary syndromes." (PMID 34884442, 2021). "Monocyte TF expression is elevated in PLHIV, mirroring the monocyte profile of PWOH with acute coronary syndromes." (PMID 34995413, 2022). "Succinobucol—a well-studied antioxidant that prevents TF expression in monocytic cell lines —has been tested in more than 6,000 patients with recent acute coronary syndromes and did not confer protective effects to justify its use therapeutically." (PMID 24586264, 2014).
acute myeloid leukemia (5 papers, 2011 to 2024). Acute myeloid leukemia (AML) is a group of neoplasms arising from precursor cells committed to the myeloid cell-line differentiation. "Overall, 20 scholars from 4 organizations published a critical review titled “Targeted Delivery of microRNA-29b by Transferrin-Conjugated Anionic Lipopolyplex Nanoparticles: A Novel Therapeutic Strategy in Acute Myeloid Leukemia”." (PMID 36299285, 2022). "Individuals with malignant hematological disorders, such as acute myeloid leukemia, who typically present with very high serum Fe, serum ferritin and transferrin saturation, are known to sustain increased mycoses, especially by Candida and Aspergilli." (PMID 21445236, 2011). "Although it was difficult to validate which TF can directly bind the PRE1 SNP due to insufficient ChIP-seq data in T/NK cells, we found the PRE1 candidate SNP rs11227311 to be located within a weak TCF3 ChIP-seq peak in Kasumi1 acute myeloid leukemia cell line [GEO GSE43834]." (PMID 31507631, 2019).
autoimmune disease (5 papers, 2012 to 2024). A disorder resulting from loss of function or tissue destruction of an organ or multiple organs, arising from humoral or cellular immune responses of the individual to their own tissue constituents. "The strong immunosuppressive ability of transferrin by targeting multiple PRRs provides a promising strategy to treat autoimmune diseases, such as IBD." (PMID 38274126, 2024). "Low levels of transferrin are now recognized as useful markers of inflammation and disease activity and correlate well with inflammatory cytokine levels in autoimmune disease." (PMID 23761727, 2013). "In Antiphospholipid Syndrome (APS), an autoimmune disease in which thrombosis development constitutes a major pathological feature, procoagulant cell activation, accompanied with TF expression and TF pathway up regulation, is one of the key events considered explaining the prothrombotic tendency." (PMID 21941583, 2012).
chronic hepatitis (5 papers, 2020 to 2024). An active inflammatory process affecting the liver for more than six months. "Looking at our earlier works, we can only see a similarity to the profile of transferrin isoforms in chronic hepatitis." (PMID 35329964, 2022). "Our previous research indicates that the altered serum profile of transferrin isoforms may be pathognomonic for a particular disease, and so, in patients with chronic hepatitis, the tetrasialotransferrin level was increased and the pentasialotransferrin level decreased." (PMID 38673719, 2024). "First-level laboratory analysis showed Hb 103 g/L, MCV 73.3 fL, ferritin 1,493 ng/mL, transferrin saturation 63%; no signs of hemolysis, chronic hepatitis, or inflammation were detected." (PMID 33281618, 2020).
esophageal cancer (5 papers, 2018 to 2024). A primary or metastatic malignant neoplasm involving the esophagus. "Another study of baseline TRF in patients with esophageal cancer found that low preoperative transferrin levels were strongly correlated with poor OS." (PMID 36983693, 2023). "Rapid turnover proteins such as prealbumin (PA), retinol binding protein (RBP) and transferrin (TF), were measured and analyzed in correlation with prognosis in 288 patients with esophageal cancer (Study 1)." (PMID 30400835, 2018).
fungal infection (5 papers, 2011 to 2024). "Four different types of AMPs (apolipophorin III, defensin, lysozyme, and transferrin) were also up-regulated upon the fungal infection." (PMID 35450074, 2022). "These facts indicate that termicin and transferrin are important immune proteins during fungal infections." (PMID 28410430, 2017). "The first group (12 genes, including DEF1, CEC1, LYSC1, transferrin, and PGRPS1) appeared to be more robustly expressed in response to both live and HK bacterial infection versus fungal infection." (PMID 38594632, 2024).
glycosylation disorders (5 papers, 2012 to 2026). "In the neonatal period, his transferrin revealed an abnormal pattern (type I congenital disorder of glycosylation (CDG)-pattern), which normalized after the neonatal period without dietary changes." (PMID 36056436, 2022). "Isoelectric focusing (IEF) of transferrin is commonly used to screen for glycosylation disorders." (PMID 34925443, 2021). "Transferrin isoform analysis showed a CDG type I pattern, consistent with a glycosylation disorder." (PMID 42220679, 2026).
head and neck cancer (5 papers, 2020 to 2025). A primary or metastatic malignant neoplasm affecting the head and neck. "GLRX5 knockdown could enhance intracellular lipid peroxidation and increase intracellular free iron, which is attributed to the upregulated transferrin and downregulated ferritin in head and neck cancer cells." (PMID 36230613, 2022).